APAF1 (apoptotic peptidase activating factor 1)
Description:
Oligomeric Apaf-1 mediates the cytochrome c-dependent autocatalytic activation of pro-caspase-9 (Apaf-3), leading to the activation of caspase-3 and apoptosis. This activation requires ATP. Isoform 6 is less effective in inducing apoptosis.
Synonyms: APAF-1; CED4
Tractability: Small molecule: a structure with a bound ligand is known; it has a high-quality binding pocket; it belongs to a druggable protein family. Antibody: its Gene Ontology location is reachable by antibodies, with high confidence. PROTAC: ubiquitination databases record sites on it; its protein half-life has been measured; a small molecule that binds it is known.
Gene: Protein-coding gene on chromosome 12 (98,645,149 to 98,735,433, forward strand). Ensembl gene ENSG00000120868.
Subcellular location: Cytoplasm
Subcellular location (Human Protein Atlas): Cytosol; Nucleoplasm; Golgi apparatus
Pathways (Reactome):
Programmed Cell Death: Activation of caspases through apoptosome-mediated cleavage; Formation of apoptosome; Regulation of the apoptosome activity; SMAC (DIABLO) binds to IAPs; SMAC(DIABLO)-mediated dissociation of IAP:caspase complexes
Gene expression (Transcription): Transcriptional Regulation by E2F6
Immune System: Neutrophil degranulation
Gene Ontology:
Molecular function: protein binding; cysteine-type endopeptidase activator activity; nucleotide binding; ADP binding; cysteine-type endopeptidase activator activity involved in apoptotic process; heat shock protein binding; identical protein binding
Biological process: positive regulation of apoptotic process; apoptotic process; intrinsic apoptotic signaling pathway; nervous system development; regulation of apoptotic process; response to G1 DNA damage checkpoint signaling; apoptotic signaling pathway; cardiac muscle cell apoptotic process; cell differentiation; cellular response to transforming growth factor beta stimulus; intrinsic apoptotic signaling pathway in response to endoplasmic reticulum stress; kidney development; response to hypoxia; response to nutrient; system development
Cellular component: apoptosome; cytosol; extracellular exosome; protein-containing complex; extracellular region; ficolin-1-rich granule lumen; secretory granule lumen; cytoplasm; nucleus
Genetic constraint (gnomAD): Loss-of-function variants: 81 observed, 146.82 expected, observed/expected ratio (o/e) 0.55, 90% interval 0.46 to 0.66. The upper end of that interval is the gene's LOEUF score, 0.66, which puts it in group 2 of 6, group 1 being the genes least tolerant of losing a copy. Missense variants: 1,204 observed, 1,440.9 expected, observed/expected ratio (o/e) 0.84, 90% interval 0.8 to 0.88. Synonymous variants: 454 observed, 488.18 expected, observed/expected ratio (o/e) 0.93, 90% interval 0.86 to 1.
Homologues: Orthologues: chimpanzee APAF1 (99% identical), macaque APAF1 (94% identical), dog APAF1 (91% identical), pig APAF1 (90% identical), guinea pig APAF1 (88% identical), mouse Apaf1 (87% identical), rat Apaf1 (87% identical), rabbit APAF1 (86% identical), tropical clawed frog apaf1 (62% identical), zebrafish apaf1 (56% identical), Drosophila melanogaster Dark (20% identical).
Diseases named in the same sentence as APAF1 in open-access papers:
APAF1 is named in the same sentence as 144 diseases in open-access papers, as found by Europe PMC text mining. Sharing a sentence is not in itself a finding about the gene and the disease. The quoted sentences say what the papers report.
ovarian carcinoma (58 papers, 2004 to 2025). A malignant neoplasm originating from the surface ovarian epithelium. "Numerous studies showed that the resistance of ovarian cancer cells to the proapoptotic effects of chemotherapy is partly due to the deficiency in Apaf-1 activity." (PMID 36297347, 2022). "miR-21 moves from the stromal cells to the ovarian cancer cells via the transport of exosomes and targets APAF1 to cause Taxol resistance in ovarian cancer cells." (PMID 29552328, 2018). "Exosomal miR-21 can directly downregulate the expression of apoptotic protease activating factor 1 (APAF1), a tumor drug resistance and apoptosis-associated protein that promotes drug resistance and aggressiveness in ovarian cancer cells." (PMID 29302403, 2017). "In this study, the authors show that miR21 is transferred through exosomes from cancer-associated fibroblasts and adipocytes to ovarian cancer cells where it modulates drug resistance by its direct target APAF1." (PMID 27021436, 2016). "In ovarian cancer, the exosomal transfer of miR21 isolated from cancer-associated adipocytes and fibroblasts (CAFs) conferred paclitaxel resistance through targeting apoptotic protease activating factor 1 (APAF1)." (PMID 33869017, 2021). "In ovarian cancer, miR-21 transfer from CAFs and Cancer Associated Adipocytes (CAAs) to cancer cells, stimulates cell motility and inhibits apoptosis thus enhancing chemoresistance, through its direct target apoptotic protease activating factor-1 (APAF1)." (PMID 30927908, 2019). "Moreover, exosomal miR-21 released by CAFs causes paclitaxel resistance by targeting APAF1 in ovarian cancer and decreasing apoptosis." (PMID 28851377, 2017). "Interestingly, loss of Apaf-1 has been reported in a variety of human cancers, such as melanoma, leukemia, ovarian carcinoma, bladder carcinoma and glioblastoma." (PMID 27863378, 2016). "Inhibition of miR-23a-3p in ovarian cancer increased APAF1 protein levels and enhanced the sensitivity of tumor cells to platinum drugs, whereas overexpression of miR-23a-3p led to decreased APAF1 expression and promoted the platinum resistance phenotype." (PMID 40710326, 2025). "Exosomal miR-21 has been shown to modulate the oncogenic potential of metastatic ovarian cancer cells by directly regulating apoptotic protease activating factor 1 (APAF1) mRNA expression through binding to the APAF1 coding sequence." (PMID 40757000, 2025). "CAAs can also cause chemoresistance by secreting exosomes, for instance, exosomal miR21s derived from CAAs can inhibit apoptosis of cancer cells and promote chemoresistance by binding to apoptotic protease‐activating factor 1 (APAF1) in ovarian cancer." (PMID 37994401, 2024). "These exosomes convey miR-21 to ovarian cancer cells, where it binds directly to APAF1, suppresses its expression, impedes apoptosis, and bestows resistance to paclitaxel." (PMID 39334866, 2024). "In another study, the downregulation of apoptotic protease activating factor 1 (APAF1) by adipocyte-derived exosomes carrying miR-21 suppressed ovarian cancer cell apoptosis and conferred resistance to paclitaxel treatment." (PMID 39697630, 2024). "Previous studies have shown that FAK promotes ovarian cancer proliferation, invasion, and metastasis by interacting with apoptotic peptidase-activating factor 1 (ASAP1)." (PMID 38560575, 2024). "These exosomes transfer miR-21 to ovarian cancer cells, directly binding to APAF1 and downregulating its expression, which inhibits apoptosis and confers paclitaxel resistance, thus promoting distant metastasis." (PMID 39334866, 2024). "Exosomal has-miR-21 inhibits ovarian cancer cell apoptosis in ovarian cancer cells while also conferring chemoresistance to cells by binding to the novel target APAF1 (apoptotic peptidase activating factor 1)." (PMID 35310909, 2022).
ovarian carcinoma (continued). "For example, recent work has shown that miR-221 promotes the stemness of breast cancer cells by targeting DNMT3b, and the exosomal transfer of stroma-derived miR21 confers chemoresistance in ovarian cancer cells through targeting APAF1." (PMID 35681792, 2022). "The direct target of miR21 was APAF1, suggesting that an increase in APAF1 in ovarian cancer cells can be used to sensitize these cells to paclitaxel." (PMID 35204377, 2022). "miRNAs, particularly miR-21, from cancer-associated adipocytes, can inhibit apoptosis in ovarian cancer cell lines (SKOV3, OVCA432) by targeting apoptotic protease-activating factor 1 (APAF-1)." (PMID 36038791, 2022). "Exogenous expression of miR-21 and miR-630 enhanced PTX resistance of ovarian cancer cells by silencing apoptotic peptidase activating factor 1 (APAF1)." (PMID 34512721, 2021). "Previously reported evidence for the role of miRNAs in regulating APAF1 expression in the context of ovarian cancer exists." (PMID 34283087, 2021). "ADSCs-Exosomal miR-21 transferred to ovarian cancer cells, inhibiting the apoptosis of ovarian cancer cells by binding to the target apoptotic protease activating factor-1 (APAF1) and giving them chemoresistance." (PMID 34709975, 2021). "Of note, miR-23a-3p over-expression together with APAF-1 downregulation characterized both platinum-resistant tumors and the ovarian carcinoma-stem-like cells (OVA-BS4 spheroids), previously reported by our group as highly resistant to platinum treatment." (PMID 34283087, 2021). "A myriad of recent research have found that APAF1 plays an important role in ovarian cancer cell proliferation and chemotherapy resistance." (PMID 32190895, 2020). "APAF1, an important molecule promoting apoptosis 17, was downregulated in series of ovarian carcinoma samples with lymph node metastasis, and at the advanced FIGO stage 28." (PMID 32284740, 2020). "CAF-derived exosomal transfer of miR-21 to ovarian cancer cells suppressed apoptosis and conferred increased chemoresistance (paclitaxel); miR-21 down-regulated its direct target APAF1, in recipient cancer cells." (PMID 32957712, 2020). "Otherwise, upregulation of APAF1 gene expression contributed to miR-186 in increasing cisplatin sensitivity of ovarian cancer cells." (PMID 32284740, 2020). "After exosomal miR-21 transship to ovarian cancer cells, miR-21 binds to apoptotic protease activating factor 1 (APAF1) and the expression of APAF1 is downregulated." (PMID 32318350, 2020). "Likewise, the vesicular transfer of miR-21 from cancer-associated adipocytes and fibroblasts to ovarian cancer cells has been reported to decrease apoptosis and promote chemoresistance to paclitaxel by downregulating the expression of apoptotic peptidase activating factor (APAF1) mRNA." (PMID 30925923, 2019). "There was a negative correlation between the expression of apoptosis protease activator 1 (APAF1) protein and miR-221 in 5 of 63 ovarian cancer tissues and 6 cell lines, including A2780, OVCAR3, SKOV3, and 3AO5." (PMID 31929798, 2019). "The APAF1 gene was confirmed to be a direct target of miR-221, which induced the proliferation of ovarian cancer cells and hindered the apoptosis of ovarian cancer cells in vitro." (PMID 31929798, 2019). "In ovarian cancer, exosomes derived from stromal cells deliver miR-21 to ovarian cancer cells, leading to chemo-resistance by targeting APAF1." (PMID 30396333, 2018). "This transfer ultimately conferred paclitaxel chemoresistance properties to the recipient ovarian carcinoma cells due to the direct regulatory effect of miR-21-5p on the transcript for apoptotic protease activating factor 1 (APAF1)." (PMID 28273813, 2017). "MiR-21, which appears several times in this review, is associated with the formation and activation of CAFs, and exosomal miR-21 released by CAFs can lead to paclitaxel resistance by targeting APAF1 in ovarian cancer." (PMID 28851377, 2017).
ovarian carcinoma (continued). "After CREB knockdown, expression of apoptosis associated molecules (Apaf-1, BAD and cleaved caspase 7) were found upregulated in ovarian cancer cells as compared to NC shRNA treated cells." (PMID 28881798, 2017). "The inverse correlation between miR21 and APAF1 mRNA expression was further confirmed by qRT–PCR analyses of the epithelial components of 38 microdissected ovarian cancer tissue samples (R=−0.493, P=0.002)." (PMID 27021436, 2016). "Functional studies reveal that miR21 is transferred from CAAs or CAFs to the cancer cells, where it suppresses ovarian cancer apoptosis and confers chemoresistance by binding to its direct novel target, APAF1." (PMID 27021436, 2016). "This was confirmed by co-transfecting ovarian cancer cells with both miR21 and APAF1 in the presence of paclitaxel." (PMID 27021436, 2016). "A transcriptome profiling analysis and subsequent validation studies demonstrated a significant decrease in APAF1 in miR21-transfected ovarian cancer cells." (PMID 27021436, 2016). "For example, the transfer of exosomal miR‐21 derived from CAFs to ovarian cancer cells led to inhibition of apoptosis and downregulation in the expression of apoptotic peptidase activating factor 1 (APAF1), as a result, resistance to treatment with paclitaxel was increased." (PMID 37994401, 2024). "Likewise, the exosomal transfer of miR-21 from CAAs to ovarian cancer cells has been reported to reduce paclitaxel-induced apoptosis via downregulation of apoptotic peptidase activating factor (APAF1) mRNA." (PMID 33670185, 2021). "As an activator of mitochondrial apoptosis, APAF-1 induces apoptosis in ovarian cancer." (PMID 34660304, 2021). "Briefly, adipocytes derived exosomes could promote drug resistance and a malignant phenotype by decreasing the expression of APAF1 in ovarian cancer cells." (PMID 34095111, 2021). "Exosomal miR21 promotes paclitaxel resistance by targeting APAF1 in ovarian cancer." (PMID 34690112, 2021). "Finally, our study further found that miR-27a regulates hypoxia resistance in ovarian cancer through APAF1." (PMID 32190895, 2020). "Next-generation sequencing technology has shown that the exosomal transfer of miR-21 from CAFs to ovarian cancer cells inhibited apoptosis and promoted resistance to paclitaxel treatment by downregulating the expression of apoptotic peptidase activating factor (APAF1)." (PMID 32545155, 2020). "Exosome-mediated miR-21 regulates paclitaxel resistance through APAF1 in ovarian cancer." (PMID 32190895, 2020). "Equally higher levels of miR-21 in CAAs were observed, and miR-21 is transported from CAAs to cancer cells, inhibiting the apoptosis of ovarian cancer cells and producing chemotherapy resistance by combining with its direct new target apoptotic protease activating factor-1 (APAF1)." (PMID 31500658, 2019). "To determine whether APAF1 is a direct downstream target of miR21, we performed a qRT–PCR analysis of ovarian cancer OVCA432 and SKOV3 cells transfected with the miR21 precursor or the negative control, to evaluate its effect on APAF1 expression." (PMID 27021436, 2016). "Inactivation of Apaf-1, a key effector of the intrinsic apoptosis pathway, and its effect on chemotherapy have been observed in several tumour types, including gastrointestinal cancer, leukemia, ovarian cancer and melanoma." (PMID 15305193, 2004). "Next-generation sequencing technology has shown that the exosomal transfer of miR-21 from CAFs to OVCA (Ovarian cancer) cells inhibited apoptosis and increased resistance to treatment with paclitaxel by reducing the expression of apoptotic peptidase activating factor (APAF1)." (PMID 39187523, 2024). "Another study reported that EVs from CAAs delivered microRNA-21 (miR21) to ovarian cancer cells, where it suppresses apoptosis and induces chemoresistance to paclitaxel through the downregulation of miR21’s direct target apoptotic peptidase activator factor 1 (APAF1)." (PMID 36670988, 2023).
ovarian carcinoma (continued). "miR-186 modulated the ovarian cancer cells' cisplatin sensitivity by downregulating PIK3R3 and PTEN while enhancing the regulation of APAF1." (PMID 34804161, 2021). "As a general tendency, PCR studies showed an upregulation of p21 and of proapoptotic genes APAF1, PUMA, BAK1 as well as a downregulation of the antiapoptotic gene survivin (BIRC5) in ovarian cancer cell lines." (PMID 31234549, 2019). "Thus, downregulation of APAF1 by miR21 may increase paclitaxel resistance in ovarian cancer cells." (PMID 27021436, 2016). "Western blot analysis of the ovarian cancer cells shows an increase in apoptotic markers, such as cleaved PARP, cleaved caspase-3, Apaf-1, Bim, Bad, and Bid, in the si-Cdk1 transfected cells than in the si-negative control cells, in a time-dependent manner." (PMID 27385216, 2016). "These literature results prompted us to analyze the gene expression profile of the five apoptosis and survival-related genes APAF1, survivin, BAK1, p21, and PUMA by PCR in all ovarian cancer cells used in this study under single and combination treatments of HDACi with cisplatin." (PMID 31234549, 2019). "Functional studies revealed that miR-21 was transferred via exosomes from cancer-associated adipocytes and CAFs to the cancer cells, suppressed ovarian cancer apoptosis and conferred chemoresistance by binding to its direct target APAF1 (apoptotic protease-activating factor 1)." (PMID 30901915, 2019). "To evaluate the effect of APAF1 on paclitaxel resistance in ovarian cancer cells in vivo, we established OVCA432 cells stably expressing doxycycline-inducible APAF1 or the control vector and injected them intraperitoneally into female nude mice, followed by paclitaxel treatment." (PMID 27021436, 2016). "APAF1 partially abrogated paclitaxel resistance, suggesting that besides downregulation of AFAP1, other mechanisms are involved in mediating the effect of miR21 on paclitaxel resistance in ovarian cancer cells." (PMID 27021436, 2016). "To determine whether upregulation of APAF1 can abrogate miR21-conferred paclitaxel resistance in ovarian cancer cells, we transfected both SKOV3 and OVCA432 cells with pre-miR21 and APAF1 or with pre-miR21 and the empty vector." (PMID 27021436, 2016). "In addition, PEA2 recurrent ovarian cancer cells, which showed significantly higher miR21 expression than did PEA1 primary cells, had significantly lower APAF1 mRNA expression than did PEA1 cells." (PMID 27021436, 2016). "To determine whether high levels of APAF1 confer paclitaxel sensitivity to ovarian cancer cells, we transiently transfected SKOV3 and OVCA432 ovarian cancer cells with the full-length APAF1 construct or the control vector pcDNA3.1 and treated them with various concentrations of paclitaxel." (PMID 27021436, 2016). "Thus, both ovarian cancer cell lines PA1 and A2780 were treated with 10, 20, and 40 nM of ST09 drug for 48 h and the expression of pro-survival factor BCL-2, pro-apoptotic proteins Bax and Bak, cytochrome C, apoptosome complex protease Apaf-1, and cleaved caspase 9 were evaluated." (PMID 34837026, 2021).